SPC24 (SPC24 component of NDC80 kinetochore complex)
Diseases named in the same sentence as SPC24 in open-access papers (continued):
Sharing a sentence is not in itself a finding about the gene and the disease.
lung adenocarcinoma (1 paper, 2017). A carcinoma that arises from the lung and is characterized by the presence of malignant glandular epithelial cells. "SPC24 is over-expressed in clinical lung adenocarcinoma samples, and high level of SPC24 is associated with advanced stages of lung tumors." (PMID 29029446, 2017). "Up-regulation of SPC24 is associated with advanced lung adenocarcinoma tumors, and tumors from smokers." (PMID 29029446, 2017). "In this study, Oncomine analysis on various datasets and IHC staining in the clinical samples revealed up-regulation of SPC24 in human lung adenocarcinoma." (PMID 29029446, 2017). "Intriguingly, our initial investigation in Oncomine datasets indicated that SPC24 is up-regulated in lung adenocarcinoma tumors as well." (PMID 29029446, 2017). "SPC24 is over-expressed in human lung adenocarcinoma tumors." (PMID 29029446, 2017). "Therefore, we first performed Oncomine analysis in published datasets to examine the SPC24 levels in human lung adenocarcinomas." (PMID 29029446, 2017). "Based on these findings, we wondered if SPC24 levels could further stratify the lung adenocarcinoma tumors according to the staging." (PMID 29029446, 2017). "Furthermore, we also observed significantly high levels of SPC24 in lung adenocarcinoma, especially the advanced stage, tumors." (PMID 29029446, 2017).
non-small cell lung carcinoma (1 paper, 2017). A group of at least three distinct histological types of lung cancer, including non-small cell squamous cell carcinoma, adenocarcinoma, and large cell carcinoma. "We knocked down SPC24 in two non-small cell lung cancer (NSCLC) cell lines, PC9 and A549, by siRNA and evaluated cell proliferation, apoptosis, and migration in the SPC24-deficient cells." (PMID 29029446, 2017). "We knocked down SPC24 in two non-small cell lung cancer (NSCLC) cell lines, PC9 and A549, and measured proliferation and apoptosis in these cells." (PMID 29029446, 2017).
pancreatic cancer (1 paper, 2024). "Among these, PLK1, SPC24, KIF2C, TOP2A, MKI67, and KIF4A, have been implicated in cancer development and serve as important biomarkers of proliferative activity in pancreatic cancer." (PMID 38250721, 2024). "Further analysis using the public database GEPIA revealed that the expression of six genes (PLK1, SPC24, KIF2C, TOP2A, MKI67, and KIF4A) was significantly associated with overall survival in pancreatic cancer patients." (PMID 38250721, 2024).
renal carcinoma (1 paper, 2025). A carcinoma arising from the epithelium of the renal parenchyma or the renal pelvis. "The results showed that the expression of SPC24 in renal cancer cells transfected with miR-501-3p mimic was decreased compared with the control groups." (PMID 39907402, 2025). "This study aimed to elucidate the effects of miR-501-3p/SPC24 axis on the behavior of renal cancer cells and to identify its prognostic value in renal cancer." (PMID 39907402, 2025). "Finally, western blot was performed to detect the expression level of SPC24 in renal cancer cells predicted by bioinformatics analysis." (PMID 39907402, 2025). "Therefore, we hypothesized that mir-501-3p plays a role in renal cancer via SPC24." (PMID 39907402, 2025). "We only found the miR-501-3p target SPC24, but did not explore the mechanism and function of SPC24 in renal cancer." (PMID 39907402, 2025).
renal cell carcinoma (1 paper, 2025). "We also found that high expression levels of SPC24 were associated with shorter OS time in patients diagnosed with renal cell carcinoma." (PMID 39907402, 2025). "The MiR-501-3p/SPC24 axis affects cell proliferation, migration, invasion, apoptosis, and prognosis in renal cell carcinoma." (PMID 39907402, 2025). "Finally, results of western blot and dual-luciferase reporter assay showed that the expression level of SPC24 could be suppressed by miR-501-3p in renal cell cancer cells, and SPC24 was directly targeted by mir-501-3p." (PMID 39907402, 2025).
tumor (17 papers, 2015 to 2026). "Immunoinfiltration analysis revealed that high SPC24 expression was associated with immunosuppressive microenvironment features, such as increased M2 tumor-associated macrophages and regulatory T cells, and decreased CD8 + T cells and NK cells." (PMID 42109651, 2026). "By scRNA-seq analysis, we found a group of DCs, which we named tumor-associated DC (TADC) because this DC subset uniquely expresses tumor-associated genes such as Pclaf, Spc24 and Top2a, highly expressed Il22ra2 in Clec7a−/− mice but not in WT mice." (PMID 36932082, 2023). "In this study, it was found that NDC80, NUF2, SPC24 and SPC25 genes were differentially expressed in tumor tissues and normal tissues and NDC80, NUF2, SPC24 and SPC25genes have diagnostic values for LUAD." (PMID 32226507, 2020). "In our study, we provide the first evidence that SPC24 functions as a tumor initiator for ATC prgression." (PMID 28423533, 2017). "Next, in vivo xenograft studies indicated that the SPC24 knockdown cells has decreased tumor size compared to the controls." (PMID 28423533, 2017). "High SPC24 expression was found in 123 cases from the 160 (76.9%) of HCC patients with diameter of tumor >5 cm, that showed its apparent prognostic value in predicting poorer DFS (p = 0.004) and OS (p = 0.035)." (PMID 26515591, 2015). "Single-cell communication analysis further suggests that SPC24 may facilitate immune escape by regulating ligand-receptor interactions between tumor cells and immune cells in TME." (PMID 42109651, 2026). "Based on the fact that miRNAs act to negatively regulate target gene expression by binding to the 3′-UTR of mRNAs, we speculated that miR-501-3p exerted its tumor suppressor and favorable prognostic effects by targeting SPC24." (PMID 39907402, 2025). "Downregulation of SPC24 inhibited growth and invasion of tumor cells and promoted apoptosis." (PMID 33553144, 2020). "Knockdown of SPC24 expression inhibited cell growth and invasion and promoted tumor cell apoptosis." (PMID 33553144, 2020). "We also demonstrated that SPC24 knockdown OS cells reduced xenograft tumor growth." (PMID 29285250, 2017). "In addition, high SPC24 expression was found in 99 cases from the 145 (68.3%) of HCC patients with one single HCC tumor nodule, and significantly correlated with shorter DFS (p = 0.003) and OS (p = 0.006)." (PMID 26515591, 2015). "The results showed that high SPC24 expression (p < 0.001), size of tumor >5 cm (p < 0.001), multiple tumor number (p < 0.001), B-C of BCLC stage (p < 0.001), the presence of PVTT (p < 0.001), and distant metastasis (p = 0.034) were significantly associated with poor DFS rate in HCC patients." (PMID 26515591, 2015). "In addition, the results of TCGA data analysis and western blot showed that the tumor suppressor effect of miR-501-3p may be achieved by targeting SPC24." (PMID 39907402, 2025). "Therefore, we speculated that miR-501-3p exerted its tumor suppressor and favorable prognostic effects by targeting SPC24." (PMID 39907402, 2025). "Given that SPC24 was strikingly up-regulated in HCC tissues, it was closely associated with multiple tumor number, tumor size > 5 cm, and the presence of PVTT, we concluded that SPC24 might serve as a novel biomarker to predict prognosis outcome for HCC patients." (PMID 26515591, 2015). "The expression levels of CDK1, SPC24, and HOXB7 were significantly higher in tumor tissues than in normal tissues." (PMID 36718148, 2023). "The NDC80 complex, including the main elements of NDC80, SPC24, and SPC25, is highly expressed in various tumors and cooperatively promotes the invasion and metastasis of tumor cells." (PMID 33778011, 2021). "Most of these interactions involved cell cycle related genes, like SPC24 and CDC20 (regulated by the anti-oncomiR miR-139), and PKMYT1 (regulated by the tumour suppressor miR-195)." (PMID 28387377, 2017).
tumor (continued). "The combined detection of NDC80, NUF2, SPC24 and SPC25 may become a new research direction in LUAD diagnosis and a new target for tumor targeted gene therapy." (PMID 32226507, 2020). "The combined detection of NDC80, NUF2, SPC24 and SPC25 may become a new research direction in tumor diagnosis and a new target for tumor targeted gene therapy." (PMID 32226507, 2020). "As above data showed that SPC24 expression is markedly higher in HCC tissues compared to non-tumor controls, we also tested SPC24 expression in human HCC cells by semi-quantitative RT-PCR." (PMID 26515591, 2015).
cancer (7 papers, 2016 to 2024). A tumor composed of atypical neoplastic, often pleomorphic cells that invade other tissues. "SPC24, a component of the Ndc80 kinetochore complex, has been implicated in the development of various cancers." (PMID 38250721, 2024). "The results indicated that NDC80 complex components were positively associated with the cell cycle, proliferation, DNA damage, and DNA repair in the majority of cancer types except SPC24." (PMID 39513104, 2024). "Taken together, these findings indicated that SPC24 served as a prognostic cancer biomarker of ATC by downregulating E-cadherin." (PMID 28423533, 2017). "The decreased viability is concomitant with increased apoptosis in SPC24-knockdown cells, suggesting SPC24 is essential for the survival of the cancer cells." (PMID 29029446, 2017). "The Oncomine expression analysis revealed that SPC24 was over-expressed in tumors from patients who had recurrent cancer after one year (p < 0.05)." (PMID 29029446, 2017). "This conflicts with our results, which may indicate that SPC24 plays different roles in different types of cancer in humans." (PMID 36718148, 2023). "On the other hand, another Oncomine expression analysis performed on a more complete dataset showed that SPC24 was consistently over-expressed in tumors from patients who regained the cancer after one, three, or five years, compared with those who had not suffered recurrence." (PMID 29029446, 2017). "On the contrary, over-expression of SPC24 enhanced cell proliferation in both cancer cell lines." (PMID 29029446, 2017). "The Kaplan-Meier curve and log-rank test analysis revealed that increased NDC80, NUF2, SPC24, and SPC25 mRNA levels were all significantly associated with the overall survival (OS), disease-free survival (DFS), disease-free interval (DFI), and progression-free interval (PFI) of pan-cancer samples." (PMID 39513104, 2024). "Consistently, over-expression of SPC24 could enhance cell migration in both cancer cell lines." (PMID 29029446, 2017). "Toward this, we performed intersection analysis on the top 200 genes having highest correlation with NDC80 complex components - NDC80, NUFS, SPC24, and SPC25 respectively at the pan-cancer level, and identified 109 overlapping genes." (PMID 39513104, 2024). "The cancer patients with higher expression of NDC80, NUF2, SPC24, and SPC25 were predicted to have worse OS, DFS, DFI, and PFI, which suggested that NDC80 complex components may be potential prognostic indicator molecules in pan-cancer." (PMID 39513104, 2024). "EMT is the key step in cancer metastasis and the decreased expression of E-cadherin is the inducer of EMT, we further study whether SPC24 is involved in regulating cell migration." (PMID 28423533, 2017). "Until now, the role of CDK1 and SPC24 coexpressions in cancer cells has not been reported." (PMID 36718148, 2023). "Furthermore, disruption of SPC24 in the normal human bronchial epithelial cell line (BEAS 2B) did not affect cell migration, suggesting SPC24 may play a more essential role in cancer progression than in the normal cell." (PMID 29029446, 2017).
adenocarcinoma (1 paper, 2017). A common cancer characterized by the presence of malignant glandular cells. "Interestingly, in one dataset, SPC24 levels are significantly higher in stage II adenocarcinoma tumors than stage I ones (p < 10-4)." (PMID 29029446, 2017).
bacterial infections (1 paper, 2022). "High expression of SPC24, NES, LOC116828075, CLSTN3, and PLAC8 was observed in the SPC24 cells of C. carbonaria, which were enriched in pathways involved in viral and bacterial infections, disease, and leukocyte transendothelial migration." (PMID 36552787, 2022).
SPC24 also shares sentences with these, for which no sentence is quoted: aneuploidy (1 paper); astrocytoma (1); brain tumours (1); Cirrhosis (1); laryngeal squamous cell carcinoma (1); pancreatic adenocarcinoma (1).